IL6 (interleukin 6)
Diseases named in the same sentence as IL6 in open-access papers (continued):
Sharing a sentence is not in itself a finding about the gene and the disease.
infection (continued). "Results show changing immunophenotypes throughout the patent period of infection represented by pro-inflammatory cytokines (IL-6), IgG and acute-phase proteins." (PMID 35529837, 2022). "The expression of IL-6, a major immune and inflammatory mediator, and the IL-6 level in our experiment began to increase at 4 h post-infection (hpi)." (PMID 35464378, 2022). "One explanation for the increased levels of IL-6 and IP-10 is the aberrant recruitment and activation of neutrophils as a result of infection." (PMID 35273264, 2022). "Of the examined cytokines IL-6 seems to offer the most potential for immunomodulatory therapy to affect both infections and HF." (PMID 35548445, 2022). "Negative hematological changes including increased inflammatory cytokines such as tumor necrosis factor-alpha (TNF-alpha), interferon-gamma (IFN-γ), and interleukin 6 (IL-6) are prominent in cases with severe infection." (PMID 35627841, 2022). "Several lines of evidence have shown that IL-6 has an important function in the early host immune reaction against infection." (PMID 35619180, 2022). "The concentrations of IL-1a, IL-1b and GM-CSF in Rag2−/− mice remained at the same high level up to 20 days of infection, whereas the expression of IL-6 reached a peak on the 4th day, and then decreased to the initial level." (PMID 36016362, 2022). "Results showed that the expression of il-6 was elevated significantly in the early phase of infection with the highest expression at 6 h after infection." (PMID 36059498, 2022). "To directly test the role of p38 signaling in IL‐6 production, we then generated Mapk14ΔM/ΔM mice by crossing Mapk14f/f with LysM‐Cre mice and challenged them with lethal N67C infections." (PMID 35635376, 2022). "The immune response is largely regulated by interleukin-6 (IL-6), which plays a vital role in the immunological response during the body’s anti-infection process." (PMID 36313375, 2022). "In particular, interleukin 6 (IL-6) is involved in the response of the human immune system to infection and cellular injury, being secreted by T cells and macrophages into the serum in case of acute and chronic inflammation." (PMID 35676309, 2022). "Serum CRP is a positive acute-phase protein produced by the liver following stimulation by IL-6 and IL-1β in response to infection, inflammation, or cancer." (PMID 36669027, 2022). "LasB, a prominent virulence factor and metalloprotease identified in PAO1, have been shown to degrade interleukin 6 (IL-6), an early immune responder to infection, and trappin-2, an antimicrobial molecule secreted from epithelial cells, in vitro and in vivo." (PMID 36312971, 2022). "Proinflammatory cytokines associated with Th17/Th1 response such as IL-6, TNF-α, and IL-1β, and neutrophil-recruiting chemokines including CCL2, CCL3, CXCL1, and CXCL2 were highly produced from day 3 to day 14 after WT infection." (PMID 35696422, 2022). "IL-6 is a multicellular cytokine with a wide range of biological activities, which participates in immune response, inflammatory response, and anti-infection defense." (PMID 35783508, 2022). "While IL-6 inhibitors are highly effective biological drugs for RA, their anti-inflammatory effects masked the signs and symptoms of infection." (PMID 35389108, 2022). "We found that the mRNA expression levels of TNF-α, IL-1β and IL-6 were significantly increased after 7 days of infection, while the expression of the three inflammatory factors was decreased upon intraocular injection of LBH589." (PMID 36171756, 2022). "The inflammatory response of the body after infection initiates the NF-Kappa B signaling pathway, which induces the expression of cytokines such as IL-6, IL1β and TNF-a to eliminate pathogen invasion." (PMID 36091044, 2022). "IL-6 levels tend to drop after an infection has been cleared from the body, and its expression/plasma levels are indicative of ongoing inflammation in tissues." (PMID 36300375, 2022).
infection (continued). "Even when using an MOI that was ten times higher, strain CL resulted in low numbers of infected THP-1-derived macrophages, except when cells were stimulated with IL-4 or IL-6, then, both strains presented similar infection rates." (PMID 36389843, 2022). "After LCN2 pretreatment for 24 h, the UPEC-infection-induced secretion of both extracellular IL-8 and IL-6 significantly were reduced in all LCN2-treated groups (p < 0.0001 compared to the 15 mM glucose treatment)." (PMID 36555403, 2022). "Numerous inflammatory cells, mainly macrophages, dendritic cells, polymorphonuclear neutrophils, and inflammatory cytokines (TGF-β, TNF-α, IL-1β, IL-6, IL-10, IL-12, and IL-23), were activated in the early stages of infection." (PMID 36233337, 2022). "Although the infection was restricted to the dam, the offspring surprisingly harbored more intestinal Th17 cells into adulthood via IL-6 signaling." (PMID 35211045, 2022). "Other cytokines (IL-5, IL-1, IL-6, and IL-18) were significantly higher in the intestine at early infection but became higher in the spleen as the infection progressed." (PMID 36187827, 2022). "It has been widely accepted that IL-6 plays a central role in response to inflammation, infection, or tissue injury by the up-regulation of acute phase response (APR) proteins including CRP." (PMID 36290585, 2022). "Upregulation of HO-1 by infection with adenovirus-HO-1 (20, 30, and 40 MOI) attenuated IL-6 secretion induced by LPS compared with infection with the vector of adenovirus (20 MOI)." (PMID 35453404, 2022). "In other words, the subset of patients that responded to the infection by secreting higher levels of IL-6 tended to show lower levels of serum Zn2+ ions." (PMID 36016660, 2022). "Here, IL‐6 is generated locally as a response to infection through the activation of stromal peritoneal cells (e.g. mesothelial cells) and resident mononuclear cells." (PMID 34618359, 2022). "The expression of hepcidin can be induced by inflammatory cytokines during infection, such as interleukin-6 (IL-6), which is regarded to deprive invading microorganisms of iron." (PMID 35276902, 2022). "NF-κB signaling is responsible for the activation of several proinflammatory cytokines, such as (TNF-α), IL-6, and IL-18, which are important for infection control." (PMID 35453567, 2022). "The presence of 4b in the nucleus in MERS-CoV-MA-WT in vivo infection partially changed the pro-inflammatory cytokine profile, by upregulating IFNß, IL-6 and IL-10, as compared to MERS-CoV-MA-mNLS, which expressed a cytoplasmic 4b." (PMID 36129908, 2022). "IL-6 is secreted during infection or inflammation by many cell types, such as endothelial and synovial cells in joints." (PMID 35214755, 2022). "Because IL-6 had the lowest predictive power for occurrence of secondary infection (unadjusted HR 1.82 (0.95–3.45), p = 0.069), it was excluded from further analysis." (PMID 35976460, 2022). "Microglia are the first defense mechanism, acting as a responder against inflammation, infection, and injury by producing inflammatory cytokines, including TNF-α and IL-6 associated with chemokines." (PMID 36704003, 2022). "Along with this, the expression of proinflammatory cytokines IL‐6 and TNFα was elevated in aged PBMCs upon infection." (PMID 35313074, 2022). "At 4 weeks post-infection, the IL-6 levels were significantly reduced in both 40 mM and 80 mM L-GSH-treated animals, compared to the untreated controls." (PMID 35453358, 2022). "The HKDM infection with WT bacteria-induced IL-6 production during all time points but at 7 h this increment was not significant." (PMID 35889053, 2022). "In patients with a dysregulated inflammatory response – characterised by the rapid and massive production of IL-6, such as during a cytokine storm in patients with infection, iMCD or cancer – it is critical to bring the inflammatory response under control." (PMID 35928820, 2022).
infection (continued). "The results indicated that MRSA and MSSA treatment of MAC-T cells increased the protein expression of TNF-α, IL-6, cleavage–Caspase3, Phospho-p65, and PrP, and then the protein expression of Bcl-2 appeared to decrease slightly with the duration of infection." (PMID 35812882, 2022). "The infection cytokines produced by interleukin (IL-6, IL-8, IL-1β), tumor necrosis factor-alpha (TNF-α), and interferon-gamma (IFN-γ) are all accompanied by a severe infection." (PMID 36421668, 2022). "In addition, CRP and IL-6 might directly accelerate protein degradation and indirectly influence important metabolic pathways to make patients frail, thereby causing patients to progress rapidly to severe or critical infection or even death." (PMID 35037900, 2022). "At Week 3 after infection, significantly elevated concentrations of proinflammatory cytokines IL-6 and IFN-γ were detected in the plasma of Erdman-infected rhesus macaques." (PMID 35412961, 2022). "Of the other covariates, older age, low levels of hemoglobin, albumin, creatinine, the higher half of IL-6, and a past history of CVD were also associated with the risk of infection-related hospitalization in the univariate Cox proportional hazards model." (PMID 35155493, 2022). "Osteoblasts and osteocytes were infected with S. aureus LS1, and the release of IL-6 was measured 24 h post infection." (PMID 35935196, 2022). "In this study, we found that E. ictaluri EseN modulates the host immune response by increasing IL-8 and IL-15, and reducing IL-12a and IL-6 cytokines during HKDM infection." (PMID 35889053, 2022). "It is well-known that TNF-α and IL-6 are classic proinflammatory cytokines functioning in many biological processes such as inflammation, infection, and wound healing." (PMID 36090347, 2022). "A dose dependent production of pro-inflammatory (TNF, IL-6 and IL-12p40) and anti-inflammatory (IL-10) cytokines in BM-DCs supernatants was observed after infection with all leptospires." (PMID 35812397, 2022). "Being an acute-phase reactant, ferritin is regulated by proinflammatory cytokines (IL-6, IL-18), which levels increase during infection, cancer, and inflammatory conditions such as rheumatologic diseases." (PMID 35936656, 2022). "CRP is an acute-phase reactant that is released in response to infection, tissue injury, and inflammation and is mediated by cytokines, such as interleukin-6, and -1." (PMID 35463642, 2022). "At 48 h, infection with M. s_Rv1515c led to significant (p < 0.001) reduction in IL-6 (5-fold decrease), reduction (p < 0.05) in IL-12 and TNF-α level, as compared to M. s_Vc." (PMID 35813825, 2022). "When interleukin-6 (IL-6) is stimulated in response to infection, inflammation, injury, or stress, the acute phase SAA proteins SAA1 and SAA2 are released into the blood." (PMID 36264449, 2022). "The infection of A549 and SK-OV-3 with HAdV26 induced changes in the expression of the IL-6, IL-8, IL-1β, and TNF-α genes." (PMID 35458402, 2022). "IL6 is an important cytokine which plays a crucial role in inflammatory processes and infection response." (PMID 34120222, 2022). "The pro-inflammatory cytokine Il-6 and antiviral type I interferon Ifnb1 were significantly up-regulated in the lung as early as 1-day post-infection, and gradually declined afterwards." (PMID 35503798, 2022). "When an infection begins, IL-8 levels rise rapidly, peaking in two to four hours and then rapidly falling in four hours, making it a useful early indicator of infection, analogous to IL-6." (PMID 35449688, 2022). "Among Th2 cytokines in the mouse lung, we found that the levels of all four marker cytokines (IL-4, IL-6, IL-10, and IL-13) progressively increased with infection time; similarly, the levels of IL-6, IL-10 and IL-13 were upregulated in the mouse brain." (PMID 35617354, 2022). "This suggests that the late IL‐6 signaling inhibits T cell function for IFN‐γ release at the late stage after an N67C infection." (PMID 35635376, 2022).
infection (continued). "Once homeostasis is disrupted by infection or tissue injuries, IL-6 is produced and contributes to host defense through the activation of immune responses." (PMID 36354990, 2022). "A second biological aspect would be a decreased innate immunological response (i.e., lower production of pro-inflammatory interleukin-6 (IL-6), after the acute phase of the infection in females)." (PMID 35806901, 2022). "Meanwhile, QKI deficient RAW 264.7 cells showed increased secretion of pro-inflammatory cytokines, such as TNF-α, IL-6, IL-1β, and decreased secretion of IL-10, post-infection." (PMID 36088389, 2022). "After infection with S. japonicum, KO rats also developed a strong pro-inflammatory response, with high production of TNF-α, IL-6, and IL-1β at all time points post-infection which reached a peak at 7 weeks post-infection." (PMID 35584107, 2022). "In mouse models of Plasmodium infection, infected IL-6 knockout mice (Il6-/-) resulted in a more severe infection when compared with infected wildtype mice." (PMID 35493515, 2022). "In this research, we demonstrate that elevated frequency of M-MDSC persists in peripheral blood of CoV2+ individuals even after 5-months post infection, as a result of persistently elevated levels of IL-6." (PMID 35812392, 2022). "It has also been shown that host immune response genes, including IL-4, CXCL10, IL-6, TNFα and IFNγ, are more active with NiV Malaysia infection compared to NiV Bangladesh." (PMID 35632678, 2022). "Taken together, these results suggest that both an early robust IFN‐α/β production and the blockage of late IL‐6 production are essential for generating adequate protective immunity against N67C infections." (PMID 35635376, 2022). "In that same time period, cells infected with the ∆EseN mutant showed significantly higher IL-6 production compared with HKDM-WT only at 1 h of post-infection." (PMID 35889053, 2022). "With increasing severity of the infection, higher levels of circulating cytokines and other inflammatory biomarkers like IL6, IL-1β, TNFα, C-reactive protein (CRP) and D-dimer occurs." (PMID 36590303, 2022). "Significantly, IL‐6 gene expression is subject to both homeostatic control and rapid induction following inflammatory challenge as a response to infection, trauma, autoimmunity or cancer." (PMID 34618359, 2022). "They determined this finding to be caused by the inhibition of Th2 involved in humoral immunity in an early stage of infection, hence emphasizing the importance of IL-6 as a marker of disease severity." (PMID 35062368, 2022). "By secreting the proinflammatory cytokines IL-1 and IL-6, macrophages and DC play an important role in the recruitment of cells at the site of infection." (PMID 35163035, 2022). "Interleukin-6 (IL-6), a multifaceted cytokine that mediates responses to infection, is involved in immune diseases and cancers." (PMID 36454780, 2022). "IL-6 also induces the synthesis of another sensitive biomarker of inflammation and infection, CRP, which increases during inflammatory response." (PMID 35873360, 2022). "Beside CRP, we found correlations between kynurenine and peak IL-6 values in the acute infection phase." (PMID 36211365, 2022). "The results showed that at the initial stage of infection, the expression levels of intestinal inflammatory factors such as IL-1β, IL-6, IL-10, TGF-β and TNF-α in the treatment group were much lower than those in the challenge group (p < 0.01)." (PMID 36431853, 2022). "The TNFα and IL-6 levels in CXCR4high MKs were comparable to macrophages from mice 3 days after L. monocytogenes infection, which are known as the primary cellular source of TNFα and IL-6 upon infection." (PMID 35904250, 2022). "By contrast, only moderate effect of the infection was measured on the colonic expression of either Cxcl2, Tnfa or Il6 at day 4 post-infection." (PMID 36266398, 2022).
infection (continued). "As a pleiotropic cytokine, IL-6 does not only play a vital role in the response to injury or infection, but also is involved in immune responses, inflammation, and hematopoiesis." (PMID 35550592, 2022). "IL-6 level was higher in gltS::Tn treated wound, suggesting more tissue damage from gltS::Tn infection." (PMID 36418899, 2022). "Both IL-6 and IL-12 are produced upon DC activation and contribute to DC/T-cell communication and immune cell recruitment to the site of infection or inflammation." (PMID 36142892, 2022). "We found that the skin lesion in diabetic rats was susceptible to infection due to the wound exposure, and the levels of TNF-α, IL-1β and IL-6 in wound tissues were significantly increased on day 7 after surgery." (PMID 35130118, 2022). "Compared with blood culture, it seems that employing the “double peaks of IL-6” pattern to predict the life-threatening infection is faster." (PMID 35757715, 2022). "Consistent with gene expression studies, we similarly detected an elevated level proinflammatory cytokine, IL-6, in the lung of aged mice compared to young mice at day 2 and day 4 post-infection (2dpi: 87.3 vs. 66.8 pg/mL, 4dpi: 73.0 vs. 49.0 pg/mL)." (PMID 34989330, 2022). "In the inflammatory response against tissue injury and infection, excessive inflammatory cytokines such as IL‐6 and TNF‐α are activated and play a crucial part in the progression of ALI." (PMID 36514748, 2022). "The relative expression of type I interferon IFN-α and IFN-β mRNA transcript was increased at approximately 60- to 150-fold following infection, while IL-1β and IL-6 recorded increase fold changes of more than 20,000- and 70,000-fold, respectively." (PMID 36317079, 2022). "IL-6 is an important inflammatory cytokine that is expressed during infection and cancer and was identified as a prominent target for clinical intervention." (PMID 36385095, 2022). "IL-6 is produced by almost all immune cells in response to infection and tissue damage and has various pleiotropic actions including B-cell activation, neutrophil and macrophage recruitments, and increased vascular permeability." (PMID 35930528, 2022). "As an example, we observed a predominant modulation of IL-6 via TLRs after infection with M. circinelloides, and TNF-α production via CTLs after infection with R. delemar." (PMID 36311802, 2022). "Some studies have suggested that IL-1β, TNF-α, IL-2, IFN-γ, and IL-6 were markedly upregulated in critical patients after infection with SARS-CoV-2 and thus can be used as biomarkers to determine the severity of disease in patients." (PMID 36069561, 2022). "IL-6 also plays a role in fighting infection, as IL-6 has been shown to be required for resistance against the bacterium Streptococcus pneumonia." (PMID 36317105, 2022). "One critical role for IL-6 in infection is driving the host fever response through brain endothelium cells." (PMID 37065537, 2022). "On the other hand, it has also been established that the production of IL-6, TGF-β, and IL-10 by macrophages is associated with a poor response to infection." (PMID 36294673, 2022). "At the same time, the levels of IL-1β were dramatically improved, while IL-6 lung levels seem to be unaffected by the infection." (PMID 36422642, 2022). "During acute inflammatory reactions, such as internal trauma, surgery, stress response, and infection, IL-6 is produced rapidly." (PMID 35774743, 2022). "One of the primary effector cytokines is IL-6, which is secreted by activated T-cells in addition to a number of other immune cell types at the site of tissue damage or infection." (PMID 36300375, 2022). "ELISA indicated that the levels of the serum cytokines TNF-α, IL-1β, IFN-γ, IFN-β and IL-6 in chickens were significantly higher at 7 dpi after infection with IBV than in the control." (PMID 35909955, 2022).